IL10 (interleukin 10)
Diseases named in the same sentence as IL10 in open-access papers (continued):
Sharing a sentence is not in itself a finding about the gene and the disease.
colitis (continued). "In the IL10−/− model, the colitis activity was also higher in EDTA groups." (PMID 33664327, 2021). "We compared abilities of CMC vs. P80 to potentiate colitis and impact human microbiota in an inflammatory environment using a novel colitis model of ex-germ-free (GF) IL10−/− mice colonized by pooled fecal transplant from three patients with active inflammatory bowel diseases." (PMID 34684567, 2021). "Besides, murine IL-10+ Bregs can prevent the recruitment of neutrophils to the sites of inflammation in a model of colitis." (PMID 33995344, 2021). "PSA protects animals from experimental colitis depending on IL-10-producing CD41 T cells." (PMID 32601832, 2021). "E. faecalis IL-10 knockout mice have shown a form of colitis phenotype." (PMID 33401586, 2021). "Moreover, the protective effects of B. fragilis NCTC 9343 against colitis induced by trinitrobenzene sulphonic acid (TNBS) or Helicobacter hepaticus largely attributed to its ability to increase the production of IL-10." (PMID 34195297, 2021). "We found that colon mucosal Il1b expression was induced to a much higher degree in DSS-induced compared to Il10−/− colitis, and that IL-1β induced Il33 from colon fibroblasts in vivo, however IL1R signaling was not required for induction of Il33 expression during DSS." (PMID 33953267, 2021). "Further, the oral administration of surface proteins from NCFM (2.29 ± 0.35 pg/ml/mg protein), MTCC 5690 (1.45 ± 0.25 pg/ml/mg protein), and MTCC 5689 (1.41 ± 0.32 pg/ml/mg protein) remarkably (P < 0.001) increased the levels of IL-10 than the DSS colitis control group." (PMID 34539597, 2021). "Therefore, Th2-colitis, defective IL-10 signaling and Tregs are involved in the pathogenesis of colitis in WAS patients." (PMID 35095863, 2021). "It is well known that IL-10 KO mice spontaneously develop colitis." (PMID 34571853, 2021). "Furthermore, in vivo, the data exhibited that neutralizing anti-IL-10 antibody can abrogate the therapeutic effects of a combination of MSCs and Wogonin on colitis." (PMID 34239686, 2021). "The colon of EV-treated mice showed reduced levels of inflammatory cytokines (TNF-α, IFN-γ, IL-1β, IL-6 and iNOS) and elevated levels of an anti-inflammatory/regulatory cytokine (IL-10), compared to that of untreated mice with colitis and TSG-6-depleted EV-treated mice." (PMID 32040478, 2020). "Previous results have shown that probiotic bacteria could downregulate TNF-α production and upregulate IL-10 in a rat model of trinitrobenzene sulfonic acid (TNBS)-induced colitis." (PMID 32983062, 2020). "Similarly, exosomes secreted by dendritic cells treated with IL-10 inhibit colitis development in 2,4,6 trinitrobenzene sulfonic acid (TNBS)-treated rats by stimulating CD4+ CD25+ Treg cells." (PMID 32365813, 2020). "The increase in IL-10 also was previously observed in chemical models of colitis." (PMID 33024049, 2020). "The influence of exosomes derived from DCs treated with IL‐10 on colitis is also documented." (PMID 32410383, 2020). "Furthermore, Gly inhibited colonic gene expression of interleukin- (IL-) 1β and promoted IL-10 expression in colitis mice." (PMID 32831636, 2020). "IL-10 is critically involved in regulating intestinal homeostasis as its total invalidation or T cell specific inactivation led to the development of a strong colitis in mice." (PMID 32117317, 2020). "The accompanying induction of anti-inflammatory mediators like Il-10 and Tgfb and cells (Tregs) might then limit the progress of colitis." (PMID 33202783, 2020). "These components acted to protect mice against colitis inflammation by significantly suppressing cytokines [γ‐interferon (IFNγ), IL‐6,IL‐1β, and IL‐17a] related to colitis pathology and upregulating anti‐inflammatory cytokine IL‐10." (PMID 32410383, 2020). "While the IL-10 model is ideal for testing pathobiont due to its incomplete penetrance, our colitis model is ideal for testing protective microbiota that could potentially attenuate colitis development." (PMID 32634481, 2020).
colitis (continued). "In addition, B. wadsworthia plays an important role in the development of IBD-like colitis in IL-10-/- mice." (PMID 33679692, 2020). "The novel Five strains formulation was as effective as Vivomixx® in reducing the development of signs and symptoms of colitis and reduced the expression of pro-inflammatory mediators including Il-6 and Tnf-α while increased the expression of Il-10 mRNA and the number of Treg." (PMID 32629887, 2020). "Treg cells can suppress ILC3-mediated colitis in an IL-10-independent fashion." (PMID 32796851, 2020). "In addition, the Gal-1 pre-treatment of DSS-induced mice significantly increased IL-10 levels compared to DSS-induced colitis group." (PMID 31999939, 2020). "Likewise, a specific B. adolescentis strain protected mice from DSS-induced colitis by increasing IL-10 levels, up-regulation of regulatory T-cells (Treg) and decreasing IL-17A positive T-cells." (PMID 32610452, 2020). "Of note, also in our previous study applying human microbiota associated IL-10-/- mice without pre-existing colitis, C. coli induced systemic TNF-α secretion, whereas splenic and blood samples were all culture-negative for C. coli." (PMID 32664563, 2020). "Likewise, B. wadsworthia increased the onset and incidence of colitis in the SPF IL-10−/− mice and the increased severity of colitis with an inflammatory signature indicative of a TH1 immune response." (PMID 32133003, 2020). "Furthermore, Vivomixx treatment has also demonstrated to induce IL-10 in a mouse model of colitis as well as to promote anti-inflammatory immune responses in experimental diabetes." (PMID 32272791, 2020). "Interestingly, Clostridium butyricum, a member of Clostridia and Clostridiales, has been reported to promote the growth of gut IL-10-producing innate immune cells and alleviate colitis in a mouse model by activating Treg and inhibiting activated macrophages." (PMID 32831636, 2020). "Interleukin 10 (IL-10)-producing B cells (B10 cells) are a subset of functional Bregs that inhibit experimental autoimmune encephalomyelitis, collagen-induced arthritis, and colitis inflammation." (PMID 32397173, 2020). "In conclusion, TOE could alleviate chronic colitis via upregulation of Foxp3+ Treg cells and production of the anti-inflammatory cytokine IL-10, which directly inhibits macrophages and pro-inflammatory cytokine synthesis, leading to reduced colitis." (PMID 33092149, 2020). "Moreover, IL-10 administration has been determined to ameliorate colitis in mice by suppressing intestinal inflammation and reducing pro-inflammatory cytokine production." (PMID 32067099, 2020). "In the IL-10−/− colitis mouse model, CXCR3 was found highly expressed in the gut." (PMID 32503584, 2020). "PF inhibited DC maturation, and PF-treated DCs could also decrease IL-17 and increase the IL-10 levels in experimental colitis, demonstrating that PF exerts its anti-inflammatory effects through immune regulation." (PMID 32472435, 2020). "Several studies showed that the PSA reduces inflammation by inducing IL-10-secreting Tregs in both chemically induced and T cell-mediated colitis model, and promotes the expression of CD39 in human leukocyte antigen-DR isotype (HLA-DR+) Treg cells to enhance the suppressive capacity of Treg cells." (PMID 33364945, 2020). "This study tested the hypothesis that deletion of the Aicda gene could protect against the development of inflammation-associated colorectal cancers, using a model of UC-like colitis in “T/I” mice deficient in TNF and IL10." (PMID 32941525, 2020). "The use of mouse models beyond DSS‐induced colitis (e.g., IL‐10−/−) could broaden the therapeutic potential of these compounds." (PMID 32153125, 2020). "One of the commonly used colitis models is the IL-10–/– mice." (PMID 32634481, 2020). "Chronic colitis in IL-10-/- mice was one of the colitis models similar to CD." (PMID 33233771, 2020).
colitis (continued). "In a TNBS-induced colitis rat model, the immunoregulatory impacts of locally submucosal endoscopic injection of AdSCs was demonstrated via the expression of Foxp3 and IL-10 mRNA ameliorating colitis injuries with fewer inflammatory infiltrates and almost complete absence of tissue edema." (PMID 33287220, 2020). "Comparable immune cell responses upon C. coli challenge have been described in human microbiota associated IL-10-/- mice without pre-existing colitis by us recently." (PMID 32664563, 2020). "To better understand how the progression of inflammation impacts the composition of the gastrointestinal microbiota, we used culture independent taxonomic profiling to identify temporal changes in the cecal microbiota of C3Bir IL-10-/- mice concomitantly with the onset and progression of colitis." (PMID 33664728, 2020). "However, IL-10 in Tregs was shown to be dispensable in the regulation of the development of a spontaneous mouse colitis model where IL-10 was ablated in FoxP3+ Tregs." (PMID 32403220, 2020). "Injection of BMSCs cultured in the presence of Galectin-3 (Gal-3) in a DSS-induced colitis mice model illustrated an increase in the sera concentration of IL-10 and an improvement in BMSC-mediated polarization towards the immunosuppressive M2 phenotype of macrophages." (PMID 33287220, 2020). "The administration of sinapic acid increased the serum levels of IL-4 and IL-10 in colitis mice." (PMID 33312339, 2020). "Furthermore, they were able to establish monocolonization of B. wadsworthia and induce colitis in GF IL-10−/− mice in the presence of TC." (PMID 32133003, 2020). "Intraperitoneal injection of these vesicles to mice treated with TNBS decreases the level of the pro-inflammatory cytokines IL-6, IL-1β, IFN-γ and IL-17a and increases the level of the anti-inflammatory cytokine IL-10 in colonic tissue, thus preventing colitis development." (PMID 32365813, 2020). "However, consumption of Emmental cheese enhanced IL10 expression in the DSS-induced colitis group, compared to all mice groups." (PMID 32156075, 2020). "Two routes of administration were also evaluated: the oral route for therapy in the Dinitrobenzene Sulfonic Acid (DNBS)-induced colitis model by administration of recombinant L. lactis SICE:IL-10 and the intranasal route applied to a model of vaccination against HPV-16-induced tumors." (PMID 33251190, 2020). "Tr1 cells can inhibit inflammatory T-cell responses and colitis by secreting IL-10 and TGF-β." (PMID 31906479, 2020). "In addition, IL-10-producing macrophages have been shown to suppress acute experimental colitis in mice 45-47." (PMID 32685014, 2020). "Similarly, in DSS-induced colitis, anti-inflammatory cytokine IL-10 can modulate intestinal inflammation through a macrophage-ROS axis." (PMID 33664740, 2020). "Additionally, CBM 588 induces intestinal IL-10-producing cells to suppress acute experimental DSS-induced colitis in mice." (PMID 33193245, 2020). "Previous studies using the IL-10-/- model of colitis have either used denaturing gradient gel electrophoresis (DGGE) for their analysis of microbial compositional or have only collected fecal pellets for 4 weeks post-colonization of germ-free mice with a SPF microbiota or at 8 and 10 weeks of age." (PMID 33664728, 2020). "The IL-10–/– mice develop spontaneous colitis with a Th1 response." (PMID 32634481, 2020). "DSS-induced colitis increased IL-10 secretion, compared to the healthy group." (PMID 32156075, 2020). "The loss of body weight in ManLAM‐WT B group was significantly slower than that in ManLAM‐IL‐10−/− B group, suggesting that IL‐10 produced by ManLAM‐treated WT B cells might attenuate the DSS‐induced acute colitis in mice." (PMID 31657484, 2020). "Moreover, administration of IPA significantly ameliorates colitis and induces IL-10-mediated anti-inflammatory pathway in vitro." (PMID 33036205, 2020).
colitis (continued). "Compared with the mice treated with ManLAM‐WT B cells, colitis scores were significantly higher in the mice subjected to the treatment with WT B, IL‐10−/− B and ManLAM‐treated IL‐10−/− B cells, mostly due to typical inflammatory changes including goblet cell loss and crypt damage." (PMID 31657484, 2020). "In addition, correcting the epithelial barrier defect in IL-10−/− mice is beneficial to attenuate colitis." (PMID 32855978, 2020). "Thus, indirubin ameliorates DSS-induced colitis by suppressing the expression of colonic TNFα, IFNγ, and IL-2 and upregulating IL-10." (PMID 32855621, 2020). "It has been suggested that these exosomes may exert their effects on DSS-induced colitis by regulating protein ubiquitination and by inducing the generation of immunosuppressive IL-10-producing M2 macrophages in the colon." (PMID 32365813, 2020). "We demonstrate B10 cells induced by ManLAM regulate Th1/Th2 cytokine balance and decrease severity of IBD compared with ManLAM‐IL‐10−/− B cell group, suggesting that ManLAM‐treated B cells have a preventive effect on colitis and this beneficial effect is mediated via IL‐10 production." (PMID 31657484, 2020). "In addition, both 10 mg/kg and 50 mg/kg sinapic acid significantly increased the mRNA levels of IL-4 and IL-10 in the colons of colitis mice." (PMID 33312339, 2020). "While the IL-10 expression were increased when colitis mice were treated by SSP." (PMID 32581849, 2020). "IL10−/− mice infected with two Helicobacter species (IL10−/−I), namely a combination of Helicobacter typhlonius (H. typhlonius) and Helicobacter mastomyrinus (H. mastomyrinus), developed colitis and colonic tumors." (PMID 32286276, 2020). "Moreover, a previous report described that Th17 cells expressing CD39 ectonucleotidase produced IL-10 and were less pathogenic than CD39-negative Th17 cells in a T cell-transfer colitis model in Rag-/- mice." (PMID 32403220, 2020). "C. jejuni-induced colitis in IL-10-/- mice is characterized by mixed Th1 and Th17 responses." (PMID 33488580, 2020). "Interestingly, deletion of OGR1 in Il10-/- female mice protected from the development of spontaneous colitis." (PMID 33324392, 2020). "Il10−/− mice develop spontaneous colitis, which is strongly dependent on the microbiota." (PMID 31396223, 2019). "Furthermore, it has been proved that probiotic Clostridium butyricum supplementation increased the levels of IL-10 to alleviate the experimental colitis in mice." (PMID 31217027, 2019). "Regulatory T cells also express IL-10 and mice deficient for IL-10 in regulatory T cells did not display systemic autoimmunity; however, these mice developed spontaneous colitis, skin and lung hyperreactivity, suggesting an organ specific role of IL-10 on regulatory T cells." (PMID 31379815, 2019). "The up-regulation of IL-10 could reduce pro-inflammatory cytokines which mediated its potential in medical therapy for colitis." (PMID 31849652, 2019). "Pre-treatment with Lactobacillus GG could prevent rat colitis associated with increased IL10 expression, and IL10 gene therapy could prevent TNBS-induced colitis in mice." (PMID 31632373, 2019). "This might be of relevance for the colitis model presented here, as the levels of IL-10 were significantly reduced in the colon of B6 DC-LMP1/CD40 mice, but not those of other backgrounds." (PMID 30653608, 2019). "We therefore utilized our gnotobiotic Il10−/− mouse model to investigate whether inactivation of the Ybt system in AIEC modulates immune-mediated colitis." (PMID 31481410, 2019). "For example, in mouse models either overexpressing IL23 or carrying a deletion for IL10, which play a pro-inflammatory and anti-inflammatory action via activation of Th17 and Treg lymphocytes, respectively, spontaneous colitis developed only in the presence of a healthy microbiota." (PMID 30934533, 2019).
colitis (continued). "In a mouse model of colitis carrying IL-10 gene deletion, a drastic reduction of mGlu5 receptor expression on enteric glial cells has been suggested as a possible protective mechanism to limit glial mGlu5 receptor-mediated stimulation of NMDA receptor and development of toxicity." (PMID 30934533, 2019). "However, replacement of the E. faecalis wild type bacteria by a ΔeutVW mutant in SIHUMI-colonized IL-10−/− mice resulted in exacerbated colitis, suggesting protective functions of E. faecalis ethanolamine utilization in complex bacterial communities." (PMID 31281321, 2019). "The protective effect of blueberry anthocyanin extract has also been confirmed in trinitrobenzene sulfonic acid (TNBS)-induced colitis mice model, where researchers found that anthocyanin treatment restored not only IL-10 secretion but also reduced serum levels of IL-12, TNF-α, and IFN-γ." (PMID 31137777, 2019). "Similarly, in the infected Colon Chips, IL-10 levels increased almost tenfold and reached levels (~ 10 pg ml−1) comparable to those observed in human patients with severe colitis induced by EHEC." (PMID 30890187, 2019). "Furthermore, in an IL-10 knockout mouse model, GPR68 deficiency provides protection against the development of colitis." (PMID 31652823, 2019). "IL-10 plays a major role in the cystatin-induced colitis and other immune-mediated disorders." (PMID 31683524, 2019). "Similarly, previous reports from our lab showed that Treg-specific (FoxP3) and Th17-specific (IL-10) genes were epigenetically-regulated in a mouse model of colitis, leading to decreased disease severity." (PMID 31681214, 2019). "In conclusion, our findings demonstrated that B. malayi derived Cystatin (rBmaCys), can alleviate the symptoms and pathology of colitis by driving the localized Th2 immune responses and upregulating IL-10 production by Tregs, and increase in innate-immune cells including IgM+B1 cells." (PMID 31683524, 2019). "In this study, we explored whether TNBS/EtOH or EtOH alone could induce sustained colitis in IL-10-/- mice." (PMID 31534535, 2019). "Moreover, IL-10-secreting B cells, IgA+ PCs and PB have been shown to be crucial in suppression of inflammation in models of arthritis, colitis, EAE, and chemotherapy, by inducing regulatory T cells and suppressing autoreactive Th1 cells." (PMID 31089128, 2019). "Moreover, GSE supplementation improves colonic tissue damage, which is probably mediated by inhibiting inflammatory cytokine gene expression and NFκB signaling in IL-10 KO colitis mice." (PMID 31689935, 2019). "Furthermore, exosomes released by interleukin-10-treated dendritic cells can inhibit TNBS-induced colitis in rats." (PMID 31749791, 2019). "Previous studies have suggested that Giardia may exacerbate colitis in genetically pre-disposed hosts (IL10-/- mice) through increased IL12p40/IL-23 production." (PMID 31260452, 2019). "Next, UC-derived strain IB51a was inoculated into germ-free Il10−/− mice to see whether a single strain was sufficient to induce colitis." (PMID 31767028, 2019). "To test this hypothesis we used IL-10-deficient (IL10−/−) mice, which spontaneously develop colitis depending on microbial exposure." (PMID 31608070, 2019). "A drastic reduction of Bacteroidaceae might also be the mechanism providing protection against colitis in antibiotic-treated Il10-/- mice." (PMID 31275292, 2019). "Similarly, butyrate was less effective in eliciting an anti-inflammatory response in the TNBS-induced colitis mouse model, vs. an injection of live F. prausnitzii or F. prausnitzii supernatant, while they both induced IL-10 and decreased IL-12 and TNF-α." (PMID 30915065, 2019). "TGF-β1 and IL-10, two main effector cytokines of Treg cells, ameliorate colon inflammation in UC." (PMID 31534467, 2019). "Besides, many drugs (e.g. olmesartan and gallic acid) that can alleviate UC have a significant reversal effect on the reduced level of IL-10 in mice with colitis." (PMID 31849642, 2019).